LINC01152 (long independently transcribed non-coding RNA 1152)
Synonyms: TCONS_00025128; CMPD; RP11-84E24.3
Gene: Long non-coding RNA gene on chromosome 17 (72,030,291 to 72,041,310, forward strand). Ensembl gene ENSG00000256124.
Diseases named in the same sentence as LINC01152 in open-access papers:
LINC01152 is named in the same sentence as 4 diseases in open-access papers, as found by Europe PMC text mining. Sharing a sentence is not in itself a finding about the gene and the disease. The quoted sentences say what the papers report.
glioblastoma multiforme (1 paper, 2021). "In glioblastoma multiforme, LINC01152 can upregulate the expression of MAML2 via the Notch signaling pathway to promote glioblastoma multiforme tumorigenesis." (PMID 34777473, 2021).
tumor (3 papers, 2016 to 2024). "SOX9‐AS1, LINC01152 and RP11‐351 J23.1 have been reported to be involved in cancer progression, with SOX9‐AS1 acting as a pro‐carcinogen in various tumours more widely." (PMID 39550706, 2024). "We found that LINC01152 was also expressed in the liver and was frequently down-regulated in HCC tissues, suggesting that it may play a role as a tumor suppressor." (PMID 27894309, 2016).
LINC01152 also shares sentences with these, for which no sentence is quoted: cancer (1 paper); glioma (1).